NAMPT (nicotinamide phosphoribosyltransferase)
Diseases named in the same sentence as NAMPT in open-access papers (continued):
Sharing a sentence is not in itself a finding about the gene and the disease.
Hepatic steatosis (continued). "Despite several studies the role of NAMPT in human NAFLD remains inconclusive and recently it has been demonstrated that inhibition of NAMPT aggravated the HFD- or oleic acid-induced hepatic steatosis through suppression of Sirt1-mediated signaling pathways." (PMID 28758929, 2017). "Thus, hepatic overexpression of NAMPT restores NAD+ levels, and thereby alleviates ethanol-induced hepatic steatosis in a SIRT1-dependent manner." (PMID 30794635, 2019). "As expected, overexpression of hepatic NAMPT led to reduced TG concentrations and serum ALT, AST levels, but this effect was abolished when SIRT1 was knocked down, suggesting SIRT1 mediates the effects of NAMPT on ethanol-induced liver steatosis and injury." (PMID 30794635, 2019). "NAMPT overexpression reduced hepatic TG levels in ethanol-fed control mice but not in Sirt6-HepKO mice, indicating SIRT6 is also required for NAMPT’s effects on alleviating hepatic steatosis." (PMID 30794635, 2019). "Although these results indicated that NAMPT could play a role in NAFLD, the effects of NAMPT on the pathogenesis of these disorders, especially in hepatic steatosis were largely unknown." (PMID 28449683, 2017). "Sirtuins depend on AMPK via stimulation of nicotinamide phosphoribosyltransferase (NAMPT), an enzyme involved in NAD+ synthesis that regulates cellular metabolism in several mammalian organs and tissues and whose inhibition worsens diet-induced hepatic steatosis in mice." (PMID 32070025, 2020).
colitis (12 papers, 2018 to 2025). Inflammation of the colon. "Our present data, which were acquired from genome-wide association studies of NAMPT in humans and mouse models of colitis, identified key driver genes in macrophages associated with IBD." (PMID 36552583, 2022). "While none of the tested NAD+ genes or proteins were significantly downregulated during experimental colitis, there was a significant increase in NAMPT, the rate-limiting enzyme in the NAD+ salvage pathway." (PMID 37744380, 2023). "Blockade of NAMPT ameliorated experimental colitis, suggesting this pathway as a potential therapeutic target." (PMID 35976971, 2022). "Our results show that the NAMPT, TLR4, and CYBB genes associated with mouse colitis share functions with those of humans." (PMID 36552583, 2022). "It has been demonstrated in mice that the blocking of NAMPT enzymatic activity with the small-molecule inhibitor FK866 ameliorates experimental colitis." (PMID 34948292, 2021). "FK866, a small molecule inhibitor of NAMPT, improved colitis induced by DSS and inhibited the tumorigenesis of inflammation-related tumors." (PMID 34925026, 2021). "For example, in disease models of colitis where NAMPT is upregulated in response to an increased turnover of NAD+ as a result of enhanced activity of NAD+-consuming enzymes, NAMPT inhibition was able to markedly supress key inflammatory processes." (PMID 30307159, 2018). "In experimental models of colitis, the chemical inhibition of the nicotinamide phosphoribosyltransferase (NAMPT) enzyme, which is involved in NAD+ biosynthesis, has been shown to promote the polarization of monocytes and macrophages toward an IL-10-producing phenotype." (PMID 40002370, 2025). "Here our analyses of single-cell RNA-seq data revealed that the levels of NAMPT and CYBB/NOX2 in macrophages were elevated in patients with colitis and in mouse models of acute and chronic colitis." (PMID 36552583, 2022). "NMN administration activated the NAMPT-dependent NAD+ biosynthetic pathway, increased NAD+ content, and inhibited DSS-induced colitis disease severity in mice, suggesting that NMN might be a new therapeutic strategy for IBD." (PMID 37371959, 2023). "FK866, a small NAMPT inhibitor, reduces mucosal NAD+ and NAD+-dependent enzymes (including PARP1, SIRT6, and CD38), NF-κB pathway activation, and inflammatory cell infiltration, thereby improving DSS-induced colitis in mice and preventing inflammation-related tumors." (PMID 37371959, 2023).
inflammatory bowel disease (12 papers, 2015 to 2024). A spectrum of small and large bowel inflammatory diseases of unknown etiology. "Nicotinamide phosphoribosyltransferase’s (Nampt) association with inflammatory bowel disease (IBD) is unclear." (PMID 30621173, 2019). "In an inflammatory bowel disease study, it was found that NAMPT could mitigate the inflammatory severity by promoting phagocytosis in inflammatory macrophages." (PMID 36604715, 2023). "A number of reports have shown that circulating NAMPT is increased in serum of patients with inflammatory disorders, including inflammatory bowel diseases (IBD), while nothing is known regarding circulating NAPRT and the presence of both cytokines in IBD patient stools." (PMID 36817780, 2023). "NAMPT-mediated NAD salvage pathway has been recently described as an immunometabolic route having inflammatory function in several disorders, including arthritis and inflammatory bowel diseases." (PMID 34202251, 2021).
ischemia (12 papers, 2013 to 2025). A hypoperfusion of the BLOOD through an organ or tissue caused by a PATHOLOGIC CONSTRICTION or obstruction of its BLOOD VESSELS, or an absence of BLOOD CIRCULATION. "The increased expression of nicotinamide phosphoribosyltransferase (Nampt) is widely acknowledged to significantly improve cerebral injuries caused by ischemia." (PMID 39095888, 2024). "Another study showed that microglia secreted nicotinamide phosphoribosyltransferase (NAMPT), which is a protein that stimulates pro-inflammatory signaling cascades via EVs upon the induction of pathological conditions like ischemia." (PMID 31795140, 2019). "NAMPT inhibition exacerbated brain infarction in a rat model of ischemic stroke, whereas local NAMPT overexpression in the brain and NAMPT enzymatic action protected against ischemia-induced cerebral strokes." (PMID 28438162, 2017). "Nicotinamide phosphoribosyltransferase (Nampt, also known as visfatin), the rate-limiting enzyme in mammalian NAD+ biosynthesis, plays several roles in protecting against ischemia, one of which was associated with the Nampt-Sirt1-AMPK neuroprotective signaling pathway." (PMID 30519156, 2018). "NAMPT, an enzyme involved in NAD production, plays a neuroprotective role by increasing or maintaining mitochondrial NAMPT and NAD levels in brain pathways following ischemia." (PMID 40162062, 2025). "After I/R injury, there was a significant increase in the NAMPT protein expression in the lung tissue, similar to the results of previous studies showing that NAMPT protein was highly upregulated in VILI and intestinal ischemia-reperfusion." (PMID 28438162, 2017). "Nicotinamide phosphoribosyltransferase (Nampt), the rate-limiting enzyme for nicotinamide adenine dinucleotide (NAD+) synthesis, and Sirt1, an NAD+-dependent histone deacetylase, protect the heart against ischemia/reperfusion (I/R)." (PMID 24905194, 2014). "In the present study, we showed that NAMPT H247A mutant and wild type proteins afflicted the same damage to neurons both in vivo and in vitro, meaning that eNAMPT exacerbated ischemia-induced neuronal injury non-enzymatically." (PMID 24392007, 2013).
hepatocellular carcinoma (11 papers, 2014 to 2025). A malignant tumor that arises from hepatocytes. "The KEGG results focused on the TNF signaling pathway, fluid shear stress, apoptosis, NF-kappa B signaling pathway, hepatocellular carcinoma, and other regulatory pathways; prompt NAMPT gene were associated with tumorigenesis." (PMID 33540574, 2021). "In hepatocellular carcinoma cells, NAMPT inhibition was associated with loss of activation of mTOR and its downstream targets." (PMID 32010616, 2019). "In hepatocellular carcinoma, nicotinamide phosphoribosyltransferase (NAMPT) can also increase the expression of PD-L1 by promoting the phosphorylation of STAT1, thereby mediating the immune escape of liver cancer." (PMID 36203966, 2022). "Serum NAMPT (visfatin) concentrations were increased in a cohort of 69 hepatocellular carcinoma patients compared to control subjects." (PMID 35565188, 2022). "NAMPT appeared to preferentially promote the cell proliferation capability of human hepatoma Hep3B, HepG2, and HuH7 cells as compared with that in normal hepatocytes." (PMID 35565188, 2022). "Visfatin, as a form of extracellular NAMPT, is susceptible to overexpression under oxidative stress in HCC cells; it then inhibits the growth of hepatoma cells." (PMID 28178643, 2017). "In cell experiments, 8 of 46 NAMPT inhibitors demonstrated a significant inhibition on cell viability, after 48 hours of incubation with HepG2 cells, a human hepatocellular carcinoma cell line with abundant NAMPT expression." (PMID 26227784, 2015). "Similarly, the serum levels of NAMPT and miR-21 were significantly higher in hepatocellular carcinoma patients than in healthy subjects." (PMID 35565188, 2022). "In addition, previous studies have shown that visfatin/NAMPT concentrations are increased in several malignancies, such as colorectal carcinoma, gastric cancer, hepatocellular carcinoma, bladder cancer, breast cancer, endometrial cancer, and other carcinomas." (PMID 36233428, 2022). "In addition to the direct involvement of NAMPT, the correlation of NAMPT levels with hepatoma growth has been studied." (PMID 35565188, 2022). "Furthermore, patients of hepatocellular carcinoma exhibiting higher serum NAMPT levels were discovered to have poor overall survival than those with lower serum NAMPT levels (p < 0.001)." (PMID 35565188, 2022). "In metastatic hepatocellular carcinoma (HCC), mass spectrometry protein analysis of HCC‐derived sEV (HCC‐sEV) identified an upregulation of nicotinamide phosphoribosyltransferase (NAMPT), a key enzyme in maintaining cellular nicotinamide adenine dinucleotide (NAD+) levels." (PMID 40237223, 2025). "This will provide novel insights concerning the potential of NAMPT and SIRT1 as therapeutic targets in hepatocellular carcinoma." (PMID 24603648, 2014).
acute myeloid leukemia (10 papers, 2020 to 2025). Acute myeloid leukemia (AML) is a group of neoplasms arising from precursor cells committed to the myeloid cell-line differentiation. "Dose- and cell type-dependent functions of NAMPT are known: although NAMPT is required for proper myeloid cell formation, hyper-activated NAMPT induces proliferation of hematopoietic stem cells and causes acute myeloid leukemia." (PMID 33546767, 2021). "Knockout of NAMPT has been shown to reduce viability of acute myeloid leukemia and colorectal cancer cells." (PMID 40526635, 2025). "For example, cells from relapsed specimens or stem-cell fractions of acute myeloid leukemia (AML) reportedly show high dependence on NAMPT, a rate limiting enzyme in the NAD salvage pathway, relative to either de novo AML or normal hematopoietic stem cells." (PMID 38092728, 2023). "It demonstrates pre-clinical efficacy toward a broad spectrum of acute myeloid leukemia (AML) subtypes by inhibiting NAMPT-dependent NAD+ production." (PMID 34187548, 2021). "Two ongoing, multicenter, promising trials of PAK4 inhibitors are testing the safety of the orally bioavailable dual inhibitors ATG-019 and KPT-9274, targeting the PAK4 and PAK4 and NAMPT in advanced solid tumors, in non-Hodgkin’s lymphoma, and in relapsed acute myeloid leukemia." (PMID 36830998, 2023). "Moreover, exposure of the acute myeloid leukemia cell line HL-60 to recombinant NAMPT or NAMPT overexpression induced myeloid differentiation of these cells per se." (PMID 32266141, 2020). "Currently there is one active Phase I trial of the dual PAK4/NAMPT inhibitor KPT-9274, in patients with relapsed and refractory acute myeloid leukemia (NCT04914845)." (PMID 40526635, 2025). "Acute myeloid leukemia samples with higher MCL1 and NAMPT gene expressions, and higher monocytic cell content present increased likelihood of poor intrinsic ex vivo response to venetoclax." (PMID 40222279, 2025).
ischemic stroke (10 papers, 2013 to 2023). A stroke disorder caused by obstruction of blood flow to the brain, due to thrombotic (local blood clot formation) or embolic (due to a blood clot or other material traveling from another site) event. "Previous reports showed that overall NAMPT protein level increased in ischemic core region and in blood serum after ischemic stroke." (PMID 24392007, 2013). "Therefore, the role of NAMPT in cerebral ischemic injury has been well concerned, and it is expected to be applied to the treatment of ischemic stroke." (PMID 35903330, 2022). "Based on the previous searches and reports, it was hypothesized that the significant protective effects of GP17 against ischemic stroke might be exerted via autophagy via Hif-1α/BNIP3 pathway or NAMPT-mediated pathway, namely SIRT1/2/3." (PMID 36572901, 2022). "As an example, heterozygous deletion of nicotinamide phosphoribosyltransferase (NAMPT) in the brain exacerbates focal ischemic stroke-induced neuronal death and brain damage, while its selective knock down in projection neurons of adult mice leads to motor dysfunction, neurodegeneration and death." (PMID 30813414, 2019). "In addition, the NAMPT protein level was elevated in ischemic region and in blood serum after ischemic stroke." (PMID 24392007, 2013). "NAMPT can increase ischemic tolerance and improve mitochondrial energy metabolism during ischemia, suggesting that NAMPT may be a key target for the prevention and treatment of ischemic stroke." (PMID 36572901, 2022). "Nicotinamide phosphoribosyltransferase (Nampt), the rate-limiting enzyme in mammalian NAD+ biosynthesis, has been found to have a positive effect on ischemic stroke treatment." (PMID 37622049, 2023). "Currently, much evidence supports NAMPT and the NAMPT-NAD+ biosynthesis pathway as therapeutic targets against ischemic stroke, including neuroprotection, vascular repair, and neurogenesis." (PMID 33149812, 2020). "Previous results from our lab13–15 have revealed that NAMPT, the enzyme for NMN production, is neuroprotective in ischemic stroke." (PMID 28386082, 2017). "Therefore, it is a promising strategy to look for neuroprotective natural agents with mitochondria protection actions mediated by NAMPT-NAD+ pathway, which has great importance for the development of novel drugs for the treatment of ischemic stroke." (PMID 33149812, 2020).
osteoarthritis (10 papers, 2017 to 2023). A noninflammatory degenerative joint disease occurring chiefly in older persons, characterized by degeneration of the articular cartilage, hypertrophy of bone at the margins and changes in the synovial membrane. "Another study found that miR-127-5p directly targeted NAMPT, which promoted the viability of osteoarthritis chondrocytes and inhibited cell apoptosis, inflammation and extracellular matrix degradation." (PMID 35518637, 2022). "This NAMPT-NAD(+)-SIRT axis has been postulated in articular chondrocytes to be involved in cartilage destruction in osteoarthritis." (PMID 28837586, 2017). "NR has been shown to play a pivotal role in the interplay between hypoxia-inducible factor-2α (HIF-2α) and the nicotinamide phosphoribosyltransferase (NAMPT)-nicotinamide adenine dinucleotide-sirtuin axis (SIRT), contributing to osteoarthritis (OA) cartilage deterioration." (PMID 37959383, 2023).
Thrombocytopenia (10 papers, 2017 to 2025). A reduction in the number of circulating thrombocytes. "Thrombocytopenia was the common dose-limiting toxicity associated with the three NAMPT inhibitors." (PMID 34068917, 2021). "Originally Nicotinamide phosphoribosyl transferase (NAMPT) inhibitor.Dose-limiting toxicities; thrombosis, thrombocytopenia, esophagitis, diarrhea, and constipation." (PMID 32708302, 2020). "In clinical trials for NAMPT inhibitors the main dose-limiting side effects were thrombocytopenia and gastrointestinal toxicity." (PMID 29156703, 2017). "One of the major obstacles to the clinical progress involving the first generation NAMPT inhibitors, FK866 and CHS828, was the occurrence of off-tumor toxicities, primarily thrombocytopenia and gastrointestinal symptoms 41-43." (PMID 37771778, 2023). "Although several NAMPT inhibitors (FK866, CHS-828, and EB-1627) have been introduced into the clinic, they ultimately failed in phase II clinical trials due to dose-limiting toxicities, including thrombocytopenia and retinal and cardiac toxicity." (PMID 40486861, 2025). "Since the NAMPT inhibitor FK866 suffers from a number of serious side effects, including thrombocytopenia, lymphopenia and anemia, as well as severe nausea and mild fatigue, we sought to identify other potentially less toxic metabolic approaches for targeting CSCs." (PMID 28223550, 2017). "Similar hematological results were obtained in another study, which showed that rats treated with various NAMPT inhibitors, including FK866 and GM1778, for periods up to 15 days demonstrated lymphopenia and reticulocytopenia (reduced lymphocytes and reticulocytes counts) but not thrombocytopenia." (PMID 34068917, 2021).
triple-negative breast carcinoma (10 papers, 2012 to 2025). An invasive breast carcinoma which is negative for expression of estrogen receptor (ER), progesterone receptor (PR), and human epidermal growth factor receptor 2 (HER2). "The combination of PARP and NAMPT inhibitors (PARPi/NAMPTi) has been explored for the treatment of triple-negative breast cancer, Ewing sarcoma and high-grade serous carcinoma (HGSC)." (PMID 41419662, 2025). "Treatment with olaparib and the NAMPT inhibitor FK866 has been reported to induce synergistic effects in triple-negative breast cancer cells." (PMID 38625917, 2024). "In a latest study, a new AS-lncRNA RP11-22N19.2, which was transcribed from the antisense strand of NAMPT, has been reported to enhance the transcriptional activity of NAMPT in triple negative breast cancer." (PMID 31448236, 2019). "In this study, we applied a selection strategy to obtain T-ALL and triple-negative breast cancer cells that are resistant to the NAMPT inhibitor FK866 and essentially observed that the metabolic plasticity of cancer cells allows them to escape the toxic insult of this drug after protracted exposure." (PMID 29541451, 2018). "Importantly, inhibition of NAMPT can increase the in vitro and in vivo effects of olaparib in models of triple-negative breast cancer, a subtype of particular unmet clinical need." (PMID 22933245, 2012). "Decreased PARP activity with NAMPT inhibitor use has been reported in several cancer models, forming the basis for preclinical testing of NAMPT inhibitors plus PARP inhibitors in Ewing sarcoma and triple-negative breast cancer." (PMID 32010616, 2019). "In addition to Ewing’s sarcoma, triple-negative breast cancer xenograft models have demonstrated that the combined inhibition of PARP and NAMPT slows tumor growth to some extent." (PMID 36160449, 2022).